CXCR4 (C-X-C motif chemokine receptor 4)
Diseases named in the same sentence as CXCR4 in open-access papers (continued):
Sharing a sentence is not in itself a finding about the gene and the disease.
infection (continued). "We therefore studied viral production effects driven by IFITM2 and IFITM3 with dual-tropic HIV-1 89.6, wherein cells were treated with the CXCR4 antagonist AMD3100 prior to and during infection." (PMID 30266929, 2018). "More in depth in vitro studies have shown that editing the CCR5 locus was able to inhibit infection from CCR5-utilizing virus, but CXCR4-utilizing virus was still able to infect cells." (PMID 30619107, 2018). "To achieve infection of both CXCR4 and CCR5 HIV-1 strains, we utilized a HuT78 cell line, which expresses an endogenous level of CD4 and CXCR4 but was transiently transduced to express CCR5 and different IFITMs." (PMID 30087232, 2018). "An additional important feature shared by PRO and BRY is the potential to inhibit de novo infection by reactivated virus through the capacity to downregulate the HIV-1 receptor CD4 as well as CCR5 and/or CXCR4 co-receptors." (PMID 30008723, 2018). "Macrophages express not only the CD4 receptor but also C-X-C chemokine receptor type 4 (CXCR4) and C-C chemokine receptor type 5 (CCR5) coreceptors necessary for efficient HIV entry and productive infection." (PMID 29772664, 2018). "In HIV infection, the expression of CCR5 or CXCR4 chemokine receptors on target cells is the primary determinant of cell tropism, with CCR5-mediated infection of CD4+ T cells predominating early in infection." (PMID 29677122, 2018). "We recently reported that CD4, CXCR4, and CCR5, when coexpressed simultaneously, form trimeric complexes that block HIV-1 binding and infection." (PMID 28360196, 2017). "The V3 loop of HIV-1 often evolves during the course of infection and allows a switch from utilization of the CCR5 coreceptor to CXCR4." (PMID 28384158, 2017). "Previously, we showed that human BBB pericytes express the major HIV receptor CD4 and co-receptors CXCR4 and CCR5, which results in their infection by HIV and compromises BBB integrity via functional alterations of endothelial cell tight junction proteins." (PMID 29311803, 2017). "A quantitative virus-cell fusion assay was used to monitor the propensity of in vitro infection of these primary cell subsets with viruses expressing envelopes of known tropism, AD8 for CCR5-using HIV-1, and NL4.3 for CXCR4-using HIV-1, respectively." (PMID 28484447, 2017). "Regarding CXCR4-tropic HIV, CXCR4 has been reported to be an absolute requirement for infection of resting CD4+ T cells purified from HIV-positive patients’ blood." (PMID 29085362, 2017). "CDM33 also inhibited HIV-1 cell-cell fusion and infection of cells expressing CD4 and either the CCR5 or CXCR4 co-receptors at similar concentrations to CD4." (PMID 28074089, 2017). "Infection of hu mice with HIV strains, such as the CXCR4-tropic strain NL4-3, usually results in progressive CD4+ T cell depletion similarly to HIV-infected individuals." (PMID 28558649, 2017). "Binding of HIV gp120 to CXCR4 and CCL19 to its receptor CCR7 activate intracellular signalling that alters actin dynamics, facilitating nuclear localisation and infection of resting T-cells." (PMID 27383184, 2016). "A reduction of surface expression of chemokine receptors CXCR4 as well as CCR1, CCR2 and CCR5 was observed in monocytes upon their infection with endotheliotropic strains (TB40E and VHLE) and clinical isolates of HCMV." (PMID 27955674, 2016). "In conclusion, CM can bind the C-type lectin DC-SIGN and block HIV-1 trans-infection of both CCR5 and CXCR4 using HIV-1 strains." (PMID 25793526, 2015). "HIV-1 entry into CD4+ cells is mediated by co-receptors CCR5 (R5 viruses) and CXCR4 (X4 viruses), and CCR5 is dominant over CXCR4 in HIV transmission from person to person and early in infection." (PMID 26172445, 2015). "The expression level of some proinflammatory molecules (e.g., CCR5, CXCR4, IL1A, IL1R1, IL8, and TNF) peaked on day 3 or 6 following infection." (PMID 25719526, 2015).
infection (continued). "In contrast, heparin can only moderately inhibit FS FIV entry and temporarily inhibit FS FIV infection at an early stage because of its weak blockade of CD134 and modest hindrance of CXCR4." (PMID 25521480, 2014). "This “stacking” of restriction factors led to a dramatic inhibition of infection by both CCR5 and CXCR4-using viruses." (PMID 24662607, 2014). "This shift in cell tropism between early and late viruses would seem counter-intuitive given that FIV infection is entirely dependent on sequential interactions between Env and CD134 and CXCR4." (PMID 25430586, 2014). "The majority of viral strains initiate infection through the CCR5 receptor, then subsequently change their coreceptor shifting to CXCR4, probably expand to more other coreceptors." (PMID 24980635, 2014). "These cells also express CD4 and both co-receptors CXCR4 and CCR5, which permits infection by both T- and M-tropic viruses." (PMID 24820173, 2014). "We have previously demonstrated that, in addition to CXCR4, TF-1 cells express the primary HIV-1 receptor CD4 on their cell surface, thereby supporting productive infection by the HIV-1 X4-utilizing (X4) IIIB strain." (PMID 25338959, 2014). "In accordance with the infection data, immature LCs express both CCR5 and CXCR4 as measured by flow cytometry." (PMID 24990163, 2014). "Prior to infection we first showed that the proportion of each CD4+ T-cell subset and the proportion of cells expressing CCR5 and CXCR4 was similar between donors, and was consistent with the findings of previous studies." (PMID 25387392, 2014). "The CCR5/CXCR4-independent phenotype was demonstrated either in ccr5 ∆32/∆32 peripheral blood mononuclear cells (PBMC) infection, and by testing the in vitro resistance to CCR5 and CXCR4 targeted inhibitors." (PMID 25421818, 2014). "At 4 days after infection, proliferation (OD of MTS) was markedly lower in the Lenti-CXCR4-siRNA group than in the SW480 group (0.92±0.06 vs 1.38±0.04, P=0.0050) and NC group (0.92±0.06 vs 1.28±0.05, P=0.0256)." (PMID 24647809, 2014). "HIV-1 is decorated with trimeric glycoprotein spikes that enable infection by engaging CD4 and a chemokine coreceptor, either CCR5 or CXCR4." (PMID 24884925, 2014). "At day 12 after infection, culture supernatants were used to infect either a pure population of GHOST-CD4/CCR5 or GHOST-CD4/CXCR4 cells, and a 80:20 mixture of GHOST-CD4/CCR8:GHOST-CD4/CCR5 and GHOST-CD4/CCR8:GHOST-CD4/CXCR4." (PMID 25421818, 2014). "To evaluate the impact of CD4, CXCR4 and CCR5 decreased expression in HIV-1 de novo infection, we treated human PBMC isolated from three donors with different concentrations of ING-B for 24 h." (PMID 24827152, 2014). "Prostratin, PMA and bryostatin-1 downregulate CD4 and CXCR4 and present mild anti-HIV activity, and ingenol-3-angelate has been shown to downregulate surface receptors blocking de novo infection." (PMID 24827152, 2014). "Whereas, as chemokine receptors were engaged in the infection, the activity of SPL7013 were found closely related to the type of HIV strain involved, including CXCR4-using (X4) and CCR5-using (R5) strains." (PMID 23884127, 2013). "In binding assays involving recombinant proteins, as well as in cellular infection assays, CX4-M1 was found to selectively recognize gp120 from HIV-1 strains that use CXCR4 for cell entry (X4 tropic HIV-1)." (PMID 24027570, 2013). "Previous studies have suggested that the inhibition of productive infection with HIV-1 by Prostratin was mediated by the down-regulation of HIV-1 receptors CD4, CCR5 and CXCR4." (PMID 23201205, 2013). "On the other hand, HIV-2MIR had produced RT activities of 3.0×105 cpm/mL 4.1×105 cpm/mL at the point of 85-90% infection through CCR5 and CXCR4 respectively." (PMID 24009735, 2013).
infection (continued). "Transmission and selection against CXCR4-using SIVsm in vivo, as well as emergence in the chronic phase of infection of variants that were transmitted but were not maintained at detectable levels early in infection have also been reported in SIV and SHIV infected monkeys." (PMID 23369442, 2013). "Such TN cell infection, although a tenth as frequent as in memory cells, contrasts with their low CCR5 expression and with the usual dogma of a preferential CXCR4-restricted infection thought to affect naive CD4 T cells during acute infection." (PMID 23691172, 2013). "Initially we determined the coreceptor usage of the Env pseudo-typed viruses by incubating TZM-bl cells with the CXCR4 inhibitor ADM3100, with the CCR5 inhibitor Maraviroc and with both before infection with the selected pseudo-typed viruses." (PMID 23874931, 2013). "The IL-6, mTOR, CXCR4 and PI3K signaling pathways were the most significantly affected at 12 weeks post-infection." (PMID 23448601, 2013). "Infection starts when gp120, the viral envelope glycoprotein, binds to CD4 and to a chemokine receptor usually CCR5 or CXCR4." (PMID 24312095, 2013). "Those mRNAs for CCL2, CCL31, CCL4, CXCL10, CCR1 and CCR5 were significantly increased following infection in both experiments in at least one time-point and CCL5, CCR9 and CXCR4 mRNA were significantly altered in one of the experiments." (PMID 24083897, 2013). "Levels of mRNAs for CCL2, CCL3L1, CCL4, CXCL10, CCR1 and CCR5 were significantly increased in at least one time point following infection in two experiments and CCL5, CCR9 and CXCR4 mRNA were significantly increased in one of the experiments." (PMID 24083897, 2013). "Stimulation of CXCR4 signalling by HIV-1 gp120 induces cytoskeleton-remodelling activity in resting T-cells, increasing the efficiency of subsequent infection with HIV-1." (PMID 23364195, 2013). "In our case we showed that, within CXCR4 signalling pathways, Gβ, H-Ras, Rho, MLC and FOS expressions were modified during early time of LPAI- and/or HPAI-infection." (PMID 24015922, 2013). "Some other genes such as CCL21, CXCR4, CCR1 and CCR7 exhibited a gradual increase during the infection." (PMID 22905138, 2012). "In the early stages of infection HIV-1 selects coreceptor CCR5, whereas, as the disease progresses, HIV-1 selects coreceptor CXCR4." (PMID 23185486, 2012). "Human immunodeficiency virus type 1, (HIV-1) infection in T cells requires viral binding to two receptors, CD4+ and a chemokine co-receptor, either CXCR4 or CCR5." (PMID 22448282, 2012). "DC-SIGN differentially enhances in-trans infection with CCR5 (R5) and CXCR4 using (X4) HIV-1 and BSSL protein interacts with CXCR4." (PMID 22412885, 2012). "In contrast, activated memory CD4+ T cells (CD4+HLA-DR+CD45RO+), which constitute the majority of activated CD4+ T cells at early stages of the infection, predominantly express CCR5,with relatively lower per-cell density of CXCR4." (PMID 22866173, 2012). "To assess the possible involvement of the CXCR4-SDF-1 axis during i.n. infection with Kim53, we quantified the levels of CXCR4 on BM neutrophils and the levels of SDF-1 in the BM and blood during infection." (PMID 23189271, 2012). "Additions ofAMD3100, a CXCR4 antagonist which prevents HIV-1 co-receptor attachment, becameineffective very soon after infection(t1/2 = 0.77 h)." (PMID 21625572, 2011). "It is possible that the discordance between the two systems stems from the HeLa-derived TZMbl cells expressing supra-physiological levels of CXCR4 and CCR5 and promoting infection via an endocytic route." (PMID 22069520, 2011). "Data described herein have identified a unique epitope of CXCR4 whose ligation not only directly inhibits CXCR4 tropic HIV-1, but also indirectly inhibits the infection of R5 tropic HIV-1 via the synthesis of natural CCR5 ligands." (PMID 22018245, 2011).
infection (continued). "We observed specific alterations in the abundance of CD4+/CCR5+ and CD4+/CXCR4+ T-cells, and concentrations of immune proteins across different HIV clades and as infection progresses." (PMID 21655330, 2011). "Infection with the human immunodeficiency virus type 1 (HIV-1) requires attachment to one of the principal chemokine coreceptors, namely CCR5 and CXCR4 for effective entry into CD4+ T-cells." (PMID 21789236, 2011). "It is known that low-level CXCR4-using variants may be selected upon CCR5 antagonist treatment, but it remains to be determined whether their presence predicts the outgrowth of a major CXCR4-using variant during natural infection or is of pathological relevance in untreated individuals." (PMID 21731496, 2011). "Expression of the chemokine receptor CXCR4, which shares the ligand CXCL12/SDF-1 with CXCR7, has been shown to be down-regulated in primary B cells upon infection by EBV." (PMID 21857817, 2011). "In comparison, mitogen-stimulated PBMCs express lower levels of CXCR4 and CCR5 and support infection via direct fusion of the viral envelope and plasma membrane." (PMID 22069520, 2011). "Our data reveal that as infection progressed a concurrent depletion of the absolute number of CD4+/CCR5+ cells and CD4+/CXCR4+ cells occurred when comparing Early and Late stage groups." (PMID 21655330, 2011). "FIV seems only to use CXCR4 as a co-receptor, but, like HIV it shifts its cell tropism during the course of infection." (PMID 22163340, 2011). "We therefore tested the ability of SIVsmm envelopes to mediate infection through human CCR2b, CCR3, CCR8, GPR1, GPR15 (BOB), CXCR6 and CXCR4." (PMID 20865163, 2010). "Real time-PCR and Western blotting were used to detect CXCR4 expression in MKN45 and HGC27 cells; and reveal it upregulated significantly in them after infection with H. pylori 26695 for 24 hours (P < 0.01, respectively)." (PMID 20699000, 2010). "In the acute phase of infection with feline immunodeficiency virus (FIV), the virus targets activated CD4+ T cells by utilising CD134 (OX40) as a primary attachment receptor and CXCR4 as a co-receptor." (PMID 20420700, 2010). "Since CXCR4 is found on a large number of memory CD4+ T cells, we allow for X4's infection of memory as well as naïve CD4+ T cells." (PMID 19680436, 2009). "It has been shown that frequent double infection can occur with CCR5- and/or CXCR4-tropic viruses, thereby generating opportunities for recombination to occur within viral populations." (PMID 19531207, 2009). "Compared to the DMSO treatment control, both TXE and VAD treatment showed significant lower Luc activities in both U87.CD4.CXCR4 and U87.CD4.CCR5 cells, indicating that they blocked HIV-1 89.6 infection." (PMID 19656383, 2009). "The mystery still now is that despite the mixed infection of CCR5-utilizing (R5) and CXCR4-utilizing (X4) HIV-1 in many AIDS patients, R5 is predominantly isolated from newly infected individuals whatever the mode of infection." (PMID 19180188, 2009). "Where CXCR4 was abundant (CLL-CD134), inhibition of infection required significantly higher concentrations of AMD3100 and even at 10 μg/ml antagonist, the degree of inhibition never exceeded 80%." (PMID 18721458, 2008). "The two most common types of infection coreceptors in humans are the CC chemokine receptor 5 (CCR5) and the CXC chemokine receptor 4 (CXCR4)." (PMID 18787705, 2008). "CXCR4 using virus was isolated from one newborn only, confirming previous observations that CCR5 is preferentially used by HIV-1 early after infection." (PMID 18820725, 2008). "Where CXCR4 was limiting (MYA-1 cells), infection with both GL8 and CPG41 was inhibited efficiently by AMD3100." (PMID 18721458, 2008). "At 1, 4 and 7 days post infection (PI), the level of cell surface CXCR4 on RH9 cells and HIV-1-infected RH9 cells were determined by flow cytometric analysis using CXCR4 monoclonal antibody (MAb) 12G5." (PMID 18190699, 2008).
infection (continued). "At early stages of infection CCR5 is the predominant HIV-1 coreceptor, but in approximately 50% of those infected CXCR4-using viruses emerge with disease progression." (PMID 18371209, 2008). "Why only R5 viruses can initiate a fresh infection and why in a significant number of subtype B infections, the viruses switch coreceptor use from CCR5 to CXCR4 in the advanced stages of the disease remains enigmatic." (PMID 18328091, 2008). "TZM-bl cells, which are permissive to HIV-1NL4-3 infection, express the viral receptor CD4 and coreceptors CCR5 and CXCR4." (PMID 18414664, 2008). "For both CXCR4 tropic and CCR5 tropic virus we found that infection became resistant to drugs that target coreceptor engagement faster when cells were preincubated at 23°C-TAS." (PMID 16725045, 2006). "Anionic polymeric candidate microbicides are thought to interfere with HIV-1-cell interactions involving cellular receptors either directly in productive infection (CD4 and CXCR4/CCR5) or in cell to cell transfer of virus (DC-SIGN etc.)." (PMID 17042959, 2006). "Here we show that CD34+ hematopoietic progenitor cell derived macrophages expressing shRNAs targeting CXCR4 and CCR5 are functionally normal and resist infection to both X4 and R5-tropic strains of HIV-1." (PMID 16109172, 2005). "During infection, HIV-1 uses CD4 as its primary receptor and a member of the chemokine receptor family like CXCR4 or CCR5 as a coreceptor." (PMID 16371160, 2005). "The chemokine receptors CXCR4 and CCR5 also play critical roles as coreceptors for viral entry during infection with T cell tropic X4 and macrophage tropic R5 HIV-1 viral strains respectively." (PMID 16109172, 2005). "The resulting complex blocks virus binding to CD4 and CXCR4/CCR5 and inhibits infection by primary virus clades A to G and group O." (PMID 15485580, 2004). "Consequently, the simultaneous disruption of both CXCR4 and CCR5 can compromise immune homeostasis and weaken host defenses against infection or vaccination." (PMID 41424846, 2026). "In the early stages of infection, the virus predominantly uses a CCR5 co-receptor (R5-tropic virus), but in later stages, it may switch to CXCR4 (X4-tropic virus)." (PMID 40699766, 2025). "CXCR4 and CXCR6 individually regulate the migration of T cells in this infection model." (PMID 40581668, 2025). "Given that CD4-GPI and CXCR4-318 seemed likely candidates to be incorporated into HIV-1 particles, and that they efficiently mediated cell–cell fusion reactions, we tested their propensity for targeting the infection of Env-expressing cells." (PMID 40284914, 2025). "Similarly, UMAP plots of BALF showed a clear shift in the CXCR4+ CXCR2+, and CCR5+ populations during infection." (PMID 40475786, 2025). "This structural incompatibility highlights the notable differences between HIV-1 and HIV-2 gp120 when bound to CXCR4, suggesting that HIV-2 may adopt a distinct assembly architecture during host cell infection." (PMID 41027939, 2025). "Given the results demonstrating the increased PD-L1+ CXCR4+ neutrophils frequency in the blood of non-survived mice, we next analyzed the distribution of these cells in the infection focus and lungs of mice predicted to survive and predicted to non-survive." (PMID 40241761, 2025). "Interestingly, HIV-1 utilizes two coreceptors, CXCR4 and CCR5, to initiate infection along with its main receptor CD4." (PMID 39998123, 2025). "CXCL12 and CXCL16 are expressed by the ependyma and periventricular region irrespective of infection, paralleling the expression of CXCR4 and CXCR6 by brain-infiltrating T cells to regulate their migration to infectious foci to the ventricular barrier." (PMID 40581668, 2025). "The effect of single substitutions was demonstrated in experiments on infecting cells expressing a mutant CXCR4 form with a lentivirus pseudotyped with the HIV-1 env; the effect of simultaneous substitution was studied in experiments on cell infection with HIV-1." (PMID 38256260, 2024).